MMP2 (matrix metallopeptidase 2)
Diseases named in the same sentence as MMP2 in open-access papers (continued):
Sharing a sentence is not in itself a finding about the gene and the disease.
Arthritis (continued). "It has also been reported that cytokine released from arthritis-affected joints, inparticular IL-1β, can stimulate the secretion of metalloproteinases (MMPs),especially MMP-2 and MMP-9, in endothelial and vascular smooth muscle cells, whichmay reduce the action of vasoconstrictor agonists." (PMID 38775546, 2024). "There is one study demonstrating that 15-LOX induces MMP-2 expression in arthritis." (PMID 33182324, 2020). "MMP-2 knockout mice showed significantly increased, while MMP-9-deficient ones significantly reduced severity of arthritis in comparison with their wildtypes, suggesting a protective and a deleterious role of these enzymes in collagen antibody-induced arthritis, respectively." (PMID 30949048, 2019). "MMP-2-deficient mice show severe arthritis, whereas MMP-9-deficient mice exhibit mild arthritis." (PMID 28441353, 2017). "Although MMP-2 may promote cartilage degradation, it suppresses the development of inflammatory joint disease in a mouse arthritis model." (PMID 24495480, 2014). "The effect of Mmp-2 was analyzed in an antibody-induced arthritis model." (PMID 21190566, 2010). "We found significantly elevated MMP-2 protein levels in knee homogenates of wild-type mice compared with MIF gene-deficient mice (wild-type, 1.3 ± 0.08 ng/mg of protein and MIF gene-deficient, 0.82 ± 0.08 ng/mg of protein; P < 0.05), pointing to an important role of MMP-2 in arthritis." (PMID 16872482, 2006). "Results showed that the severity of arthritis was lower in the etoposide treated mice as monitored by the overall arthritis index, histopathological picture and decreased levels of pro-inflammatory cytokines, lower levels of reactive oxygen species and reduced levels of MMP-2." (PMID 34107951, 2021). "Therefore, taking advantage of increased MMP-2 expression on the cell surface within arthritis tissues may constitute a reasonable approach to MMP-2-mediated therapeutics." (PMID 27741237, 2016). "MOIG treatment inhibited the production of IL-1β, IL-6, IL-8 and TNF-α, and reduced the matrix degradation enzymes expressions of MMP2 and MMP3 in TNF-α-stimulated FLSs, thereby blocking the spread of arthritis to distant joints." (PMID 39444614, 2024). "MMPs such as MMP2, MMP3, and MMP9 are up-regulated in arthritis, leading to damage to bones and cartilage of joints via activation of IL1β, TNFα, and many other cytokines." (PMID 37765197, 2023). "The antioxidant and anti-inflammatory properties of melatonin and 5-MTX in arthritis models have demonstrated that the protective effect is created by reducing the expression of MMP-1 and MMP-2." (PMID 33628825, 2021). "Sixteen days after arthritis induction 57–60 kDa MMP isoform, 75 kDa MMP-2 and 92 kDa MMP-9, but at 30 days only 57–60 kDa isoform increased significantly in the ankle joint homogenates of both arthritic groups as compared to the non-arthritic controls." (PMID 30949048, 2019). "Expression of MMP-2 (gelatinase A) and MMP-9 (gelatinase B) are also elevated in arthritis, but interestingly they have distinct roles in RA." (PMID 30949048, 2019). "We also tested in SIC the levels of MMPs (MMP-2 and MMP-9), one of the key mediators of tissue damage in arthritis." (PMID 23762133, 2013). "The arthritis gene located within Cia5d controls the FLS production of soluble membrane-type 1 (MT1)-matrix metalloproteinase (MMP) and activation of MMP-2." (PMID 18706093, 2008). "Serum concentrations MMP-1, MMP-3, and MMP-9, acutely adapt to mechanical loading, with rapid increases at the beginning of physical activity followed by a fairly rapid stabilization thereafter; moreover, MMP-2, MMP-3, and MMP-9 are highly expressed in patients afflicted by arthritis." (PMID 36835076, 2023). "There are no other sources of information on the MMP2 regulation by WNT5A in arthritis, but in cancer cells the two types of results can be found." (PMID 33178184, 2020).
Arthritis (continued). "Similarly, MMP-2- and MMP-3-knockout mice are manifested with more severe arthritis than the wild-type mice." (PMID 32518385, 2020). "Furthermore, a function study reported that the S100A8 stimulation in chondrocytes induces upregulation of mRNA levels of MMP-2, MMP-3, MMP-9, and MMP-13 and ADAMTS-4 and ADAMTS-5 in experimental murine arthritis, which is similar to our findings." (PMID 31815654, 2019). "We therefore injected into arthritic mice recombinant TGF-β with MMP2, ApoE, C1q, Ttr and Thbs1 but with no success, we did not observed arthritis resolution compared to SuperMApo injection." (PMID 30542342, 2018). "Expression of MMP2, MMP9, and MMP13 genes, which are related to the endochondral ossification pathway and bone remodeling, was also increased in the arthritic paw up to day 8 after arthritis induction." (PMID 26801240, 2016). "We determined that a gene located within the arthritis severity regulatory Cia5d interval specifically controls the invasive properties of FLSs via the regulation of the production of soluble MT1-MMP and activation of MMP-2." (PMID 18706093, 2008). "In a previous study, genetic ablation of MMP-2 resulted in an exacerbated level of collagen antibody-induced arthritis, while the lack of MMP-9 attenuated it compared to the wildtype mice indicating suppressive role of MMP-2 and pro-inflammatory role of MMP-9 in the process." (PMID 30949048, 2019). "MMP2, MMP9, and EMMPRIN are members of the MMP protein family and are involved in breakdown of the extracellular matrix in normal physiological processes, such as reproduction, embryonic development, and tissue remodeling, as well as in disease processes, such as arthritis and metastasis." (PMID 25928011, 2015). "Indeed, knockout mouse experiments revealed that the absence of MMP-9, but not of MMP-2, reduces arthritis progression." (PMID 19664212, 2009). "Unlike MMP-2 KO mice, MMP-9 KO mice showed reduced levels of Antibody-Induced Arthritis, indicating that MMP-9 enhances arthritis in this model." (PMID 32982752, 2020). "In addition, the expression of other MMPs, such as MMP-2, MMP-3, and MMP-9, is elevated in arthritis, and these enzymes degrade non-collagen matrix components of joints." (PMID 34209006, 2021).
lymph node metastasis (56 papers, 2006 to 2026). "In TC, the increased expression of MMP2 facilitates cell invasion and associated with lymph node metastasis." (PMID 38568917, 2024). "Overexpression of CD147 is associated with lymph node metastasis, whereas overexpression of MMP-2 is associated with a higher FIGO stage, increased myometrial invasion, and high histologic grade." (PMID 36982551, 2023). "MMP2 is significantly overexpressed among matrix metalloproteinases in thyroid cancer and was associated with lymph node metastasis." (PMID 34035807, 2021). "Among MMPs, MMP-2 and MMP-9 are collagenase that can selectively degrade type IV collagen, a major component of ECM; overexpression of MMP-2 or MMP-9 is associated with more lymph node metastases, distant metastases and poor survival in head and neck SCC." (PMID 31850235, 2019). "The expression levels of Bcl-2, Twist1, E-cadherin, N-cadherin, Vimentin and MMP-2/9 were significantly associated with lymph node metastasis, and the differences in the pathologic grades were significant." (PMID 28032603, 2017). "Expression of MMP-2 and cytokeratin 19 are independent risk factors for prediction of lymph node metastasis and survival." (PMID 26472188, 2015). "This overexpression was associated with lymph node metastasis (P = 0.008), tumor differentiation (P = 0.020), distant metastasis (P = 0.026), MMP-2 (P = 0.035), and MMP-9 expression (P = 0.022)." (PMID 26599012, 2015). "Furthermore, the study found that higher MMP-2 levels were associated with larger tumor size, lymph node metastasis, and distant metastasis." (PMID 38089632, 2023). "We observed significant publication bias in the analysis of the association of MMP2 overexpression with survival (P < 0.05), ER status (P = 0.003), and lymph node metastasis (P = 0.003), as well as MMP9 overexpression with lymph node status (P = 0.045) and TNM stage (P = 0.042)." (PMID 33568081, 2021). "In addition, stronger MMP2 expression was found in the front edge of cancer cell invasion, suggesting that MMP2-positive cancer cells have stronger invasive characteristics and are associated with lymph node metastasis." (PMID 35397606, 2022). "Perturbed MMP2 gene expression was the only molecular biomarker independently associated with poor outcome (hazard ratio 1.38, 95%CI 1.16–1.65, p < 0.001) together with size of the tumor (HR 1.47, 95%CI 1.10–1.96, p < 0.01) and lymph node metastasis (HR 1.71, 95%CI 1.27–2.30, p < 0.001)." (PMID 33321813, 2020). "Higher expression levels of MMP-2, MMP-9, and MMP-14 were associated with advanced tumor stage, lymph node metastasis, and poorer prognosis." (PMID 38089632, 2023). "Synchronous high expression of both p-ATF1-T184 and MMP2, lymph node metastasis and distant metastasis were prognosis factors of GC in univariate and multivariate Cox regressions (P = 0.010, P = 0.035, and P < 0.001, respectively)." (PMID 35397606, 2022). "High expression levels of MMP-2 and MMP-9 are associated with an increased risk of developing lymph node metastasis in PTC patients." (PMID 36077709, 2022). "Our meta-analysis demonstrated that MMP2 and MMP9 overexpression in tumor cells was associated with poor survival, larger tumor size, lymph node metastasis, distant metastasis, higher clinical stage, and histological grade in patients with BC." (PMID 33568081, 2021). "Previous reports have shown that ESCC tumor invasion depth and lymph node metastasis are related to MMP-2 28,29." (PMID 33390848, 2021). "MMP2 overexpression conferred a higher risk to distant metastasis (OR = 2.69, 95% CI 1.35–5.39, P = 0.005) and MMP9 overexpression correlated with lymph node metastasis (OR = 2.90, 95% CI 1.86 – 4.53, P < 0.001)." (PMID 33568081, 2021). "PTP1B promotes invasion and metastasis by regulating the PTEN-AKT/pAKT pathway and promoting the expression of metalloproteinase 2 (MMP2) and MMP7, which is associated with lymph node metastasis." (PMID 34638706, 2021).
lymph node metastasis (continued). "Several studies have shown that the expression of MMP2 correlates with lymphatic and vascular invasion, and lymph node metastasis." (PMID 32960785, 2020). "Analyses of biopsy specimens from OSCC patients revealed that the BRD4 and MMP2 expression levels were correlated in the cancerous regions, and both were highly expressed in lymph node metastasis cases, including delayed metastasis." (PMID 32499570, 2020). "Lymph node status correlated with MMP-2 plasma level, which was distinctly elevated only in patients with lymph node metastasis." (PMID 32751899, 2020). "Immunohistochemical results showed that overexpression of MMP2 in thyroid tissues is associated with the occurrence of PTC and lymph node metastasis (LNM)." (PMID 29949618, 2018). "Dysregulation of MMP2 and MMP9 is frequently present in head and neck cancers and is associated with lymph node metastasis and poor prognosis." (PMID 28963552, 2017). "MMP-1 expression in EC cells is associated with poor prognosis; MMP-2 and MMP-3 expression is positively correlated with depth of invasion, lymph node metastasis, and vessel permeation." (PMID 26916665, 2016). "Thyroid carcinomas produce elevated levels of MMP2, which has been correlated with the presence of lymph node metastasis." (PMID 27409830, 2016). "High levels of MMP-2 and MMP-9 in serum were strongly connected with lymph node metastasis and, additionally, activities of MMP-2 and MMP-9 were significantly increased in metastatic than in non-metastatic lymph nodes." (PMID 27110764, 2016). "The protein expression of MMP-2 and MMP-9 was positively associated with the status of lymph node metastasis and TNM stage (P<0.001)." (PMID 23935727, 2013). "Lastly, MMP-2 is among the recently identified predictive genes that show a positive correlation with lymph node metastasis." (PMID 18349846, 2008). "Previous studies have determined that both MMP-2 and MMP-9 are associated with lymph node metastasis and poor outcome in HNSCC." (PMID 18349846, 2008). "Furthermore, both BRD4 and MMP2 were highly expressed, not only in the cancerous tissues of patients with lymph node metastasis (N(+)) but also in cases with delayed metastasis (N(d.m.))." (PMID 32499570, 2020). "MMP-2 overexpression positively correlated with lymph node metastasis." (PMID 23320037, 2012). "Interestingly, the authors hypothesized that the expression of MEG3 in CAFs may enhance their capability to remodel the ECM through MMP-2 expression and thus favor the propensity for lymph node metastases." (PMID 36077709, 2022). "Furthermore, MMP-2 expression was significantly associated with lymph node metastasis (positive vs negative: OR 1.91, 95% CI 1.17–3.12)." (PMID 25816052, 2015). "Receiver operating characteristic (ROC) curves were constructed to evaluate the performance of preoperative serum MMP-2 in diagnosing PTC, predicting lymph node metastasis (LNM), and predicting structurally persistent/recurrent disease (SPRD)." (PMID 29949618, 2018). "It has been demonstrated that MMP-2 and MMP-9 expression is positively correlated with the depth of invasion, lymph node metastasis, and vessel permeation." (PMID 25617627, 2015). "The expression of SPARC is correlated significantly with MMP2 mRNA expression in esophageal tumor tissue specimens, and high SPARC expression was found to be correlated significantly with lymph node metastasis and poor patient prognosis." (PMID 21152079, 2010). "Moreover, the upregulation of MMP-2 and MMP-9 has been consistently reported in OSCC patients with lymph node metastasis." (PMID 39408625, 2024). "SIRT1 could also upregulate matrix metalloproteinase-2 (MMP-2) level in BC cell lines by its deacetylation activity, exhibiting a direct correlation with advanced TNM stage, higher rates of lymph node metastasis (LNM) and poor survival of patients." (PMID 35927590, 2022).
lymph node metastasis (continued). "The activation ratio of MMP-2 was higher in the malignant tissues of patients with lymph node metastasis as compared with those without lymph node metastasis." (PMID 23320037, 2012). "In addition, the lymph node status was correlated with the expression of MMP2 in plasma, that is, the expression of MMP2 was significantly increased in patients with lymph node metastasis compared with those without." (PMID 34804973, 2021). "Additionally, MMP2 expression in lymph node metastasis is significantly higher than that in non-metastatic tissues." (PMID 34521883, 2021). "In studies comparing the expression of MMP-2 in CRC and the clinical-pathological variables, there was a statistical significance of strong expression of this enzyme in cases of stage III and IV, tumor size and venous invasion, lymph node metastasis and distant metastasis." (PMID 32813775, 2020). "In several studies comparing MMP-2 expression levels in CRC and clinicopathological variables, a significance was observed regarding the strong expression of this enzyme in stages III and IV (TNM), tumor size and venous invasion, lymph node metastasis, and distant metastasis." (PMID 24737953, 2014). "Furthermore, significant correlation was observed between MMP-2 expression and lymph node metastasis, but not other clinocopathological features, such as TNM stage, tumor size, distant metastasis, histological grade, estrogen receptor status and progesterone receptor status." (PMID 25816052, 2015). "In oral SCC, the degree of activation of MMP-2 and MMP-9 is significantly higher in malignant tissues of patients with lymph node metastasis than in those without lymph node metastasis." (PMID 24988190, 2014).
aortic aneurysm (53 papers, 2009 to 2026). A ruptured aneurysm located in the wall of the proximal portion of the descending aorta proceeding from the arch of the aorta. "The addition of a miR-29a precursor in VSMCs was associated with a reduced expression of MMP-2, a metalloprotease shown to have increased expression in aortic aneurysms." (PMID 32872191, 2020). "We aimed to evaluate the contribution of TLR4 and MMP2 polymorphisms individually and complex interactions between gene and risk factors in susceptibility to aortic aneurysm (AA) and its subtypes." (PMID 30530865, 2019). "We and other research groups have shown that the progression of aortic aneurysm in the mouse model of MFS is associated with a significant increase in MMP-2 and -9 expression within the aortic wall." (PMID 30765726, 2019). "We also examined the interaction effect between TLR4 and MMP2 polymorphisms on the risk of aortic aneurysmal diseases." (PMID 30530865, 2019). "Previously, using the mouse model of MFS, we were able to show that progression of aortic aneurysm was associated with significant increases in the expression levels of matrix metalloproteinase (MMP)-2 and MMP-95–8." (PMID 30765726, 2019). "In the present study, we intended to investigate the potential effects of genetic polymorphisms in TLR4 and MMP2 individually and complex interactions in susceptibility to aortic aneurysmal diseases in a Chinese Han population." (PMID 30530865, 2019). "Elevated MMP-1 and MMP-2 have been strongly associated with ruptured atherosclerotic plaques and aortic aneurysms." (PMID 28676082, 2017). "A recent study showed attenuation of experimental aortic aneurysm formation in mice after use of unsaturated fatty acid causing reduced expression of MMP-2 and MMP-9." (PMID 26539497, 2015). "Mmp2-deficient mice showed reduced aortic aneurysm formations in CaCl2-induced TAA and AAA models." (PMID 31857579, 2019). "Recently, another research group found that lipid oxidation might be linked to an aortic aneurysm since it could promote elastic fibers degradation and high-MMP2 expression." (PMID 28573134, 2017). "The main MMPs involved in aortic aneurysms are gelatinase A (MMP-2) and gelatinase B (MMP-9) and both are capable of degrading the extracellular matrix because they elevate elastolytic and collagenolytic activity when compared with normal aortic tissue." (PMID 40521351, 2025). "Natural products can protect against aortic aneurysm due to their inhibitory activity on MMP-2 and -9." (PMID 40565017, 2025). "The inclusion of MMP2 as a mechanistic focus was based on its established role in aortic aneurysms, despite the limitations of clinical trials targeting broad MMP inhibition to treat AAAs." (PMID 40202792, 2025). "Numerous studies have demonstrated increased levels of active-MMP2 in the aortic wall of aortic aneurysm or dissection." (PMID 39022686, 2024). "This leads to thinning of aortic wall and smooth muscle cell (SMC) release of matrix degrading enzymes, such as matrix metalloproteinase 2 (MMP2), which mediates aortic aneurysm pathogenesis." (PMID 36776267, 2023). "In BAV, a key element of aortic aneurysm pathogenesis is the imbalance between the proteolytic effect of MMP-2 and TIMP1." (PMID 35563383, 2022). "Overexpression of MMP2 in smooth muscle cells and MMP9 in neutrophils and macrophages can cause degenerative changes in the middle layer of the artery in aortic aneurysms, and knockout of MMP2 and MMP9 can inhibit the development of thoracic aortic aneurysms." (PMID 35463768, 2022). "Increased viability of MMP-2 can cause arteries to dilate, and increased vitality of MMP-9 can cause rupture of aortic aneurysms." (PMID 33403385, 2021). "Cells from aortic aneurysms have been noted to have migratory abnormalities as well as upregulation of matrix degrading enzymes, such as MMP2 and MMP923,24." (PMID 29520069, 2018).